RNF126P1 (ring finger protein 126 pseudogene 1)
Gene: Transcribed processed pseudogene on chromosome 17 (57,045,521 to 57,046,445, forward strand). Ensembl gene ENSG00000261192.
Diseases named in the same sentence as RNF126P1 in open-access papers:
RNF126P1 is named in the same sentence as 4 diseases in open-access papers, as found by Europe PMC text mining. Sharing a sentence is not in itself a finding about the gene and the disease.
RNF126P1 shares sentences with these, for which no sentence is quoted: atypical hemolytic-uremic syndrome (1 paper); microangiopathic hemolytic anemia (1); renal failure (1); Thrombocytopenia (1).